CCL2 (C-C motif chemokine ligand 2)
Diseases named in the same sentence as CCL2 in open-access papers (continued):
Sharing a sentence is not in itself a finding about the gene and the disease.
tumor (continued). "Importantly, although tumor cells secrete chemokines like CXCL1/2, CCL2, and IL-8 that attract myeloid cells to the tumor microenvironment (TME), they typically do not secrete chemokines for which CAR T-cells express receptors." (PMID 39317919, 2024). "This work provides the first evidence of the direct role of miR‐210‐3p on hypoxia‐induced CCL2 downregulation resulting in impairment of monocyte infiltration and its conversion towards the M1 phenotype in LUAD cells, 3D lung tumor spheroids, and tumor xenograft zebrafish model." (PMID 35658112, 2024). "Chemoattractants, produced by malignant cells and the stromal tumor compartment, such as C-C Motif Chemokine Ligand 2 (CCL2), vascular endothelial growth factor (VEGF), CXCL12 (SDF1) and colony-stimulating factor-1 (CSF-1), recruit monocytes from the bloodstream that migrate into tumor site." (PMID 38397187, 2024). "Furthermore, the Mast-CCL2 subgroup may activate the NF-κB signaling pathway through TNF-α, potentially playing a role in the recruitment of peripheral blood monocytes to the tumor by expressing CCL2 and CCL4 genes, thereby exerting effects in BCa." (PMID 39308672, 2024). "In solid tumor TMEs, CCL2 can interact with its receptors to recruit CCR2+ TAMs, MDSCs, and Th2 cells, creating an immunosuppressive microenvironment that favors tumor progression and accelerates the colonization and growth of metastatic tumor cells, thus contributing to tumor development." (PMID 38769475, 2024). "Tumor growth and angiogenesis: CAFs derived from ASCs secrete various growth factors and cytokines, such as fibroblast growth factor 2 (FGF2), vascular endothelial growth factor (VEGF), and CCL2, which promote both tumor growth and the formation of new blood vessels." (PMID 39519109, 2024). "Thus, we analyzed the secretory factors in cultures of astrocytes and tumor cells and cocultures of these cells and found increased abundances of various soluble factors, such as MIF, CCL2, IL-6, and IL-8, primarily in astrocyte cultures compared to cultures of the other cell types." (PMID 38825648, 2024). "In addition, we confirmed that tumor cell-intrinsic MELK inhibition is beneficial in stimulating M1 macrophage polarization, hindering M2 macrophage polarization and inducing CD8 + T-cell recruitment, which are dependent on the alteration of CCL2 expression." (PMID 38970074, 2024). "However, a phase II clinical trial enrolling patients with metastatic castration-resistant prostate cancer found that carlumab, a monoclonal antibody targeting CCL2, was well-tolerated but lacked significant anti-tumor activity as a monotherapy." (PMID 38649887, 2024). "In addition to the cytotoxic effects inducing the apoptosis of immune cells residing in the TME, a reduced production of inflammatory factors such as CCL2, CXCL8, and VEGF was observed, resulting in a diminished migration of tumor-promoting immune cells, including MDSC, to the TME." (PMID 37513979, 2023). "In addition, the elevated exosome miRNA-155 during the co-culture of tumor cells and adipocytes can promote the production and release of adipocytes CCL2 and CCL5 by targeting the SOCS6/STAT3 pathway, thereby regulating the function and polarity of macrophages and promoting tumor progression." (PMID 37666813, 2023). "Interestingly, on subgroup analysis of MYCN non-amplified tumor samples, we found that CCL2 expression was higher in advanced stage tumors, while it exhibited decreased expression in MYCN-amplified advanced stage tumors." (PMID 37964011, 2023). "CCL2 levels were not affected by regorafenib in blood but increased in tumor tissue, which may contribute to drug resistance and prevent complete tumor remission." (PMID 37013652, 2023). "CAFs then support tumor growth through the promotion of angiogenesis via the secretion of a variety of growth factors such as VEGF, PDGF, EGF, FGF2, FGF5, GDF15 and the secretion of immunosuppressive cytokines including TGF-β, IL-6, CXCL12, CCL2, LIF, and GAS6." (PMID 36167831, 2023).
tumor (continued). "Consequently, the downregulation of CCL2 and TROP-2 expression may decrease the TME inflammatory status and reduces the tumor cells growth in CRC cases." (PMID 37760840, 2023). "Tumor-derived IL-6 induces endothelial IL6-STAT3 signaling, which in turn may lead to increased plasma concentrations of cachexia-promoting factors like C-C motif chemokine ligand 2 (CCL2/MCP-1), commonly described in CAC patients." (PMID 37222464, 2023). "This silencing will then activate the release of C-C motif chemokine ligand 2 (CCL2) from tumor cells, allowing myeloid cell recruitment via their C-C chemokine receptor type 2 (CCR2), which in turn will promote the chemotaxis and chemokinesis of tumor cells, and therefore tumor cell invasiveness." (PMID 37583899, 2023). "Extending this work, the group later described that the MDSC-recruiting and protumorigenic features of FAP/STAT3/CCL2 signaling were conserved in iCCA, reiterating the importance of CAFs and FAP signaling in generating an immunosuppressive stroma that is permissive for tumor progression." (PMID 36708970, 2023). "However, inflammatory monocytes recruited by CCL2 can also differentiate into monocyte-derived dendritic cells, which can present antigens to CD8 + and CD4 + T cells, thus assisting and stimulating the adaptive anti-tumor immune response." (PMID 36451019, 2023). "Thus, delivering CCL2 KO MSCs into the TME may prevent immunosuppressing TAMs and facilitate the M1-polarized macrophages, promoting anti-tumor function." (PMID 36672395, 2023). "The CCL2 and CSF1 metastatic sites might draw MφNPs into the metastatic tumor regions." (PMID 38111068, 2023). "Prior studies have noted the ability of CAAs in secreting high abundance of IL-6, IL-1β, CCL2, chemokine (C–C motif) ligand 5 (CCL5), tumor necrosis factor-α (TNF-α), vascular endothelial growth factor (VEGF) and leptin, which could enhance tumor invasion and immune escape." (PMID 37127625, 2023). "Some investigators have analyzed the effect of the TME on γδ T cell recruitment in a preclinical transplantable B16 melanoma model, where human Vδ1 T cells use the CCR2/CCL2 pathway to migrate toward the tumor, where they exert critical non-redundant anti-tumor functions." (PMID 38077392, 2023). "Using C.M. collected from MSCs treated with siRNA targeting either IL1RN or CCL2, we also observed the inhibition of proliferation; however, the mechanism was not likely due to the IL-28 related pathway, since the tumor cells were not sensitive to exogenous IL-28 at high concentrations." (PMID 36672395, 2023). "However, treatment of mice with the PDGF receptor antagonists crenolanib or trapidil failed to reduce CCL2 production in 4T1 tumor-bearing mice." (PMID 37208442, 2023). "The 4-culture tumor spheroids were characterized by spatial proximity of PSC and monocytes to the endothelial cells and a cytokine signature with increased concentrations of CXCL10, CCL2, and IL-6, which have been observed in PDAC patients and associated with poor survival." (PMID 37519820, 2023). "We document pharmacological inhibition of pro-inflammatory cytokines POSTN and CCL2 in the TME following combinatorial treatment of erlotinib+MLN0128 and propose that the effectiveness of the dual therapy is a result of both direct anti-tumor activity and modulation of the TME." (PMID 36831214, 2023). "Therefore, it is possible that tumor-infiltrating myeloid cells are an important source of CXCL10 and CCL2 after short-course ATRi plus RT, and that prolonged daily ATRi negatively impacts these myeloid cells and reduces CXCL10 and CCL2 production." (PMID 36810257, 2023). "The present study demonstrates that elevated preoperative AMC level may serve as a predictor of higher risk of tumor marker-negative TGCT, and CCL2 plays an important role in TAMs infiltration and MMPs secretion to induce tumorigenesis of TGCT." (PMID 37352031, 2023).
tumor (continued). "Contrary to our hypothesis, neutralization of GM-CSF in 4T1 tumor-bearing mice or transplantation of Gmcsf-/- 4T1 cells did not alter the serum CCL2 level or tumor Ccl2 mRNA expression level." (PMID 37208442, 2023). "Moreover, CCR2 and CSF1R surface proteins of MφNP may interact with CCL2 and CSF1, respectively, which are known for recruiting monocytes and macrophages into the tumor tissue." (PMID 38111068, 2023). "When the NPs arrived at the tumor, the high intratumoral concentration of HA could directly recruit lymphocytes and induce the secretion of chemokines, such as CXCL9, CXCL10, CXCL11, and CCL2, through the cascading amplification effects." (PMID 36479842, 2023). "Expression profiling of tumor tissues from treated mice revealed a unique gene signature induced by erlotinib+MLN0128, consisting of downregulation of immunosuppressive chemokines in the tumor microenvironment, including C-C motif chemokine ligand 2 (CCL2) and periostin." (PMID 36831214, 2023). "Moreover, both TNC and CCL2 tumor levels correlated negatively with markers of M1 macrophage status (IL6) and positively with markers of M2 macrophage status (CD168 and Arg1), with a higher correlation of TNC than CCL2 at both 3 and 11 weeks." (PMID 37176074, 2023). "In addition, whether CCL2 and TGF-β1 can promote tumor progression in addition to affecting the tumor immune microenvironment and the regulatory mechanism of MYL9 require further investigation." (PMID 37926835, 2023). "Evaluation of cytokine changes in the tumor microenvironment by ELISA-based analysis of tumor lysates demonstrated that combined blockade elevated the levels of cytokines IFN-γ, TNF-α, IL4, M-CSF, GM-CSF, and CCL2, while it suppressed the immune suppressive cytokine TGF-β." (PMID 37449205, 2023). "In fact, the permeability of HCMEC/D3 cells has been reported to be increased in stress conditions and pro-inflammatory cytokines and chemokines such as TNFα and CCL2 via signaling pathways as JNK, PKC or NFκB, which could be included in the EVs produced by tumor cell lines." (PMID 37297006, 2023). "Further, the chemoattractant properties of CCL2 are not exclusive to tumour promoting macrophages." (PMID 37108548, 2023). "Many inhibitors, such as inhibitors of ANG2 (Trebananib), CCL2/CCR2 (Carlumab and PF-04136309), CCL5/CCR5 (Leronlimab, Maraviroc, and Maraviroc), CSF-1/CSF-1R (Emactuzumab and Pexidartinib), and VEGF have been shown to inhibit macrophage recruitment for tumor growth." (PMID 37211559, 2023). "In the tumour immune microenvironment, proteasome activation factor PA28γ could activate the NF‐ĸB signalling pathway of oral squamous carcinoma (OSCC) cells and enhance the expression of CCL2, which promote tumour angiogenesis and reduce the survival rate." (PMID 36872292, 2023). "CCL2 increased the expression level of the CCR1 ligand CCL3 in MAMs via CCR2, and the signaling generated by the CCL3/CCR1 interaction enhanced and stabilized the cancer cell-MAM interaction in part through integrin α4 binding to VCAM1 expressed on tumor cells in an autocrine manner." (PMID 37208442, 2023). "This lack of impact on the monocytes in our knockout tumor may be due to a coordinated increase in Ccl2 production by the knockout cell line, which is known to recruit monocytes to the tumor microenvironment." (PMID 37505292, 2023). "Importantly, the tumor immune dysfunction and exclusion (TIDE) algorithm showed that in CCL2-high GBM group, the expression of CD274, CTLA4, HAVCR2 and other immune checkpoints were significantly increased, and the immune checkpoint blockade (ICB) therapy was accordingly more responsive." (PMID 38057698, 2023). "CCL2, also known as monocyte chemoattractant protein-1, and CCL5, also referred to as RANTES (regulated on activation, normal T cell expressed, and secreted), are key molecules in macrophage chemotaxis and activation that have been reported to promote tumor proliferation." (PMID 36571444, 2023).
tumor (continued). "Similarly, recent studies have revealed that CCL2 could activate the PI3K/AKT pathway and resist tumor cell apoptosis and autophagy, thereby leading to resistance to major anticancer agents, such as taxanes, platinum drugs, tamoxifen, and temozolomide." (PMID 36077785, 2022). "FBXW7 can inhibit CCL2 gene transcriptional activation by negatively regulating NOTCH expression levels; and inhibition of CCL2/CCR2 signaling has been shown to suppress tumor metastasis demonstrating an important role of the FBXW7/NOTCH/CCL2 axis in the regulation of cancer metastasis." (PMID 35346215, 2022). "Finally, we observed that the CCL2/CCR2-mediated trafficking of CCR2b.B7-H3.CAR-T cells to the tumor within the brain is tumor specific since we did not observe accumulation of CCR2b.B7-H3.CAR-T cells in the opposite hemisphere of the brain." (PMID 35443752, 2022). "Additionally, some cytokines and chemokines may also participate in this process, since M2 TAMs also secrete IL-8, IL-10, TGF-β, CCL2, CCL4, CXCL13, and other soluble mediators that are capable of inducing tumor growth in vitro and in vivo." (PMID 36532078, 2022). "When compared to exosomes from tumor cells without heat stress (TEX), heat-stressed tumor cell-derived exosomes (HS-TEX) had more chemokines (CCL2, CCL3, CCL4, CCL5, and CCL20), HSPs (HSP60, HSC70, HSP70, and HSP90), and adhesion molecules (e.g., CD54 and CD86)." (PMID 35158999, 2022). "The plasma concentration of CCL2 in 4T1 tumor-bearing mice was diminished in the 100 IU+cal group as compared to 100 IU and 1000 IU+cal groups, while no change was observed in 67NR tumor-bearing mice and an increased concentration in healthy BALB/c mice in calcitriol-treated groups." (PMID 36230508, 2022). "However, in this model, myeloid recruitment occurred predominantly after initial tumor cell invasion into the liver; thus, CCL2 involvement at the pre-metastatic stage is not yet certain." (PMID 35954395, 2022). "CCL2 and CCL7, both highly expressed in tumor microenvironment, can recruit various immune cells (such as myeloid-derived suppressor cells, MDSCs) to form an immune-suppressive microenvironment, allowing tumor cell to evade from the body's immune surveillance and supporting tumor cell proliferation." (PMID 36347994, 2022). "TAMs-related functions are also regulated by several genes, including C-C motif chemokine ligand 2 (CCL2), C-C motif chemokine ligand 18 (CCL18), TANK-binding kinase 1 (TBK1), and IFN regulatory factor 3 (IRF3), whose signaling pathway is activated during tumor angiogenesis." (PMID 36432658, 2022). "TAMs originate from peripheral blood monocytes that infiltrate into the tumor microenvironment in response to cytokines such as VEGF, colony stimulating factor-1 (CSF1), CXC motif chemokine ligand-12 (CXCL12) and various CC motif chemokine ligands (CCL) such as CCL2." (PMID 36421358, 2022). "Targeting CCR4 could be a promising migrastatics strategy to reduce cancer cell motility and metastasis in HNSCC without promoting tumor relapse observed during the interruption of CCL2 inhibition." (PMID 35177591, 2022). "Furthermore, NGS analysis revealed that NF-κB/RELA targets including CCL2, CXCL8, EDN1, IL-1β, IL-6, and SERPINE1 were further reduced and several potential tumor suppressors, such as FABP3, FADS2, FDFT1, SEMA6A, and PCK2, were synergistically induced by the Gefitinib-+IKK16 treatment." (PMID 36358633, 2022). "Finally, we showed that the KRAS blocker deltarasin acts to downregulate IL1R1 (interleukin-1 receptor 1) expression in KRAS-mutant tumor cells and that the proposed KRAS/CCL2/IL1B signature is enriched in human cancers with high KRAS mutation frequencies, in which it portends a dismal prognosis." (PMID 35327394, 2022). "In addition to inducing immunogenic cell death and type I IFN secretion, anthracyclines promote the recruitment of CCL2/CCR2–dependent functional antigen-presenting cells (APCs) into tumor sites but not into tumor-draining lymph nodes." (PMID 35656295, 2022).
tumor (continued). "Antibodies designed to broadly deplete TAMs, such as CCL2/CCR2 and CSF-1/CSF1-R neutralising mAbs have performed poorly in the clinic as single agents, characterised by both a lack of effect on specific pro-tumoural subsets and collateral inhibition of anti-tumour TAM activity." (PMID 35020853, 2022). "The enrichment of Tregs in the tumor seems to be driven by the expression of the chemokine receptors CCR4 and CCR7 that drives their migration and also the chemo attractants such as monocyte chemotactic protein-1 (MCP-1) also known as CCL2 and C-C chemokine ligand 22 (CCL22)." (PMID 36338731, 2022). "Currently, clinical trials of human neutralizing antibodies against CCL2 are focused on carlumab and MLN1202 that can effectively block the differentiation of monocytes to macrophages and reduce immune cell recruitment after binding to CCL2, exhibiting broad anti‐tumor effects." (PMID 35702353, 2022). "Considering the critical roles of CCL2 on macrophage migration, the different results between in vitro and in vivo experiments might have been due to the fact that CCL2 might recruit more TAMs in the TME, leading to a high ratio of M2-like phenotypic TAMs in tumor tissues." (PMID 35851310, 2022). "However, in advanced tumors, anti-inflammatory mediators released in the TME, such as CSF-1, CCL2, IL13, IL4, IL10, and prostaglandin E2 (PGE2), can revert the anti-tumor program and favor a switch of TAM into an M2 phenotype with pro-tumor and immunosuppressive functions." (PMID 35163420, 2022). "Those chemokines were preferably expressed by neutrophils throughout the tumor stroma but not by tumor cells or by the adjacent non-malignant tissues, while patients whose tumors had lower levels of CCL2+ or CCL17+ cells had longer survival times than those with higher numbers of these cells." (PMID 34200529, 2021). "Thus, targeting the CCL2/CCR2 axis may be a plausible avenue in cancer therapy, particularly for many solid tumors belonging to the “cold tumor” family." (PMID 34804061, 2021). "Since a previous study revealed that enhanced production of CCL2 from tumor tissue may be involved in TLR7/8-induced antitumor effects, we also evaluated Ccl2 expression in MC38 cells in the presence of IMQ and found that IMQ significantly upregulated the expression of Ccl2 in MC38 cells." (PMID 34439104, 2021). "The secreted proteins CCL2, TNFRSF21, PLC, COL1A1, PlGF, PAI and IL-6 are all known to be involved in cancer progression and have pro-tumorigenic properties, suggesting that cancer cells can be shifted towards a more aggressive state by tumor microenvironmentally induced secretion." (PMID 34090457, 2021). "We further found that ITGA3 was negatively correlated with monocyte markers (CD86), TAM markers (CCL2 and IL10), and M2 macrophage markers (CD163 and MS4A4A), suggesting that ITGA3 could regulate the polarization of TAMs and promote tumor growth and metastasis." (PMID 34094951, 2021). "The considerable CXCL1-dependent inhibition of the expression of CCL2 and CCL28, also endowed with an immunostimulating, but also pro-tumoral effect, emphasizes the critical role of the final equilibrium among the multiple microenvironmental signals in driving BCSC fate and tumor behavior." (PMID 34195201, 2021). "On the other hand, the area of tumor colonies was in negative correlation with CCL2 expression." (PMID 33671869, 2021). "Interestingly, in the model, the CCR2 antagonist had no therapeutic effect on tumor cells with no CCL2 expression." (PMID 34804061, 2021). "Mint3 depletion attenuates chemotaxis toward CCL2 in macrophages/inflammatory monocytes due to the defect in ATP production via glycolysis without affecting the expression levels of CCR2 in macrophages, those of CCL2 in metastatic lungs, and serum in tumour-inoculated mice." (PMID 34621018, 2021).